SHBG (sex hormone binding globulin)
Diseases named in the same sentence as SHBG in open-access papers (continued):
Sharing a sentence is not in itself a finding about the gene and the disease.
Obesity (continued). "Additionally, obesity, particularly abdominal adiposity, increases estradiol production and bioavailability due to a reduction in hepatic synthesis of sex hormone-binding globulin (SHBG) in postmenopausal women." (PMID 25360510, 2014). "Apart from their direct effects, adipokines may also interact with sex hormones, sex-hormone binding globulin, insulin-like growth factor or the binding proteins to mediate the development of obesity-related cancers." (PMID 24205276, 2013). "Obesity and hyperinsulinemia have for example been related to low levels of SHBG." (PMID 23781314, 2013). "Whether SHBG is a biomarker for obesity and the metabolic syndrome or if it is more directly implicated in the physiopathology of the metabolic syndrome is less clear." (PMID 23781314, 2013). "Obesity influences endogenous hormones by increasing adrenal secretion of androgens, enhancing conversion of androgens to oestrogens and reducing plasma levels of sex hormone-binding globulin, which results in higher levels of biologically active oestrogen." (PMID 21343939, 2011). "In females the free androgen index (FAI) [FAI = 100× (FT/SHBG)], as a marker of PCOS, may be misleading in obese patients because obesity reduces sex hormone-binding globulin (SHBG) levels." (PMID 21188021, 2010). "It is said that the production, metabolism and bioavailability of estrogen are enhanced in the subcutaneous tissues of obese males as a result of activation of aromatase, a decrease in sex-hormone-binding globulin (SHBG) and for these reasons obesity has been reported as a risk factor for MBC." (PMID 17543123, 2007). "Therefore, we hypothesize that an increase in SHBG during obesity treatment will contribute to a decrease in sexual desire by increasing bound testosterone compared to free testosterone." (PMID 41404471, 2026). "However, obesity and hyperinsulinemia, which are frequently observed in adolescents with PCOS, exacerbate diagnostic challenges by altering key biomarkers such as the FAI and SHBG, making it difficult to distinguish PCOS from other anovulatory conditions." (PMID 40861046, 2025). "Moreover, the SHBG rs1799941 polymorphism in non-diabetic obese males is found to be a genetic risk factor for obesity-based hypogonadism." (PMID 40427034, 2025). "Additionally, obesity triggers oxidative stress and ovarian inflammation, stimulating the production of androgens, while enhancing peripheral aromatization of estrogen and reducing the production of sex hormone-binding globulin (SHBG) in the liver." (PMID 40060378, 2025). "Regarding SHBG, our results showed that plasma SHBG levels increased after 1 month BS in all patients which has also been described previously in women with polycystic ovary syndrome and obesity and recently reported in several meta-analysis, where SHBG rise from 25 to 130%." (PMID 38183592, 2024). "Thus, obesity, particularly central obesity and steatosis, inhibits production of sex hormone binding globulin (SHBG) contributing to lower circulating total T, through a lower T binding capacity, with only little affection of the free testosterone (FT) concentration." (PMID 38609526, 2024). "Meta-analysis of two studies in men, which included a total of 44 participants (28 with obesity, 16 with T2D), total intervention groups n = 3, and two studies in women who were obese with a total of 19 participants, were analysed for the effects of aerobic exercise training on SHBG." (PMID 39467940, 2024). "Obesity could increase functional circulating androgens by decreasing hepatic SHBG secretion." (PMID 38256617, 2024). "Thus, it can be assumed that BMI (obesity), being a significant modifier of the level of SHBG (reduces its level) and SHBG-related sex hormones (increases their level) in the organism, can also have a prominent effect on the correlating nature of SHBG candidate genes with BC." (PMID 38672173, 2024). "Moreover, the SHBG levels decreased as obesity indicators increased." (PMID 37249458, 2023).
Obesity (continued). "SHBG, BioT, and estradiol may partly mediate the effect of obesity on male health." (PMID 37483981, 2023). "As, in our study, we found that the NAFLD PCOS adolescents had a higher BMI than non-NAFLD PCOS adolescents, we can hypothesize that the development of obesity in girls with PCOS further reduced SHBG levels, which in turn have triggered the development of NAFLD." (PMID 36421197, 2022). "Decreased SHBG may lead to obesity-related endocrine mechanisms and chronic inflammation." (PMID 36267567, 2022). "How obesity may perturb several hormonal aspects of puberty is currently under debate; however, it may involve sex hormone-binding globulin (SHBG), a liver-produced glycoprotein that binds sex steroids with high affinity in blood regulating their bioavailability." (PMID 33689083, 2021). "In addition, chronic conditions such as liver cirrhosis, obesity, and hyperinsulinism may increase levels of sex hormone binding globulin (SHBG), which binds circulating T and limits its biological effects." (PMID 34207687, 2021). "Growing scientific evidence shows obesity-related conditions such as insulin resistance, type 2 diabetes, and the metabolic syndrome as well as obesity-related systemic markers (e.g., leptin, adiponectin, SHBG, insulin and the IGF axis and C-reactive protein) are associated with breast cancer." (PMID 34066392, 2021). "In addition, our results suggest that plasma adiponectin levels may play a more important role than TNFα in influencing plasma SHBG levels in our prepubertal population with obesity." (PMID 33689083, 2021). "Decreased SHBG is the predominant factor in men with mild obesity, whereas suppression of the hypothalamic-pituitary-testicular axis by inflammatory cytokines and leptin might be mainly responsible for low testosterone in men with severe obesity." (PMID 32535783, 2020). "Indeed, low total testosterone (TT) primarily reflects reduced concentrations of sex hormone-binding globulin (SHBG) in mild obesity, with no clear evidence of clinical androgen deficiency or defective spermatogenesis." (PMID 31817436, 2019). "Thus, it may be reasonable to regard SHBG as contributing to protection from metabolic syndrome accompanying inflammation and obesity." (PMID 30046278, 2018). "One study with a hypocaloric diet + anti-obesity drug (Orlistat) intervention reported a statistically significant difference between groups (p < 0.05) following the intervention; however, there was also a statistically significant difference in SHBG at baseline between the groups (p < 0.05)." (PMID 28885578, 2017). "In the light of these findings, SHBG represents an alternative marker for pediatric NAFLD risk stratification and in certain children at higher risk for NAFLD and MetS, may be a useful biomarker perhaps prior to the development of obesity." (PMID 26761949, 2016). "Therefore, genetic factorsthat lower SHBG levels may potentially affect MetS defining traits, including highblood pressure, and obesity." (PMID 25647406, 2015). "Furthermore, a cross-sectional study among AA pre-menopausal women found that upper body fat distribution (WHR > 0.8) was a better marker for a high risk hormonal profile (high estrogens, androgens, and prolactin, and low sex hormone binding globulin) for breast cancer than general obesity." (PMID 24118876, 2013). "(2020) reported that SHBG overexpression protected male, transgenic mice against HFD-induced obesity as well as metabolic disease." (PMID 41180177, 2025). "BMI-predictive proteins included established obesity markers and obesity-related proteins, including adiponectin, CRP, IGFBP1, IGFBP2, PRG4, SHBG, apolipoproteins (APOA4, APOF) and inflammatory response proteins (A2M, APCS, LBP, HSPG2, HP, AOC3, ITGB1, VNN1)." (PMID 39972214, 2025). "As expected, obesity contributed significantly to higher values of BMI, insulin, glucose, HOMA-IR, blood pressure, triglycerides and FAI and lower levels of HDL-C and SHBG." (PMID 39958263, 2025).
Obesity (continued). "We found evidence suggesting a mediating role of SHBG, fasting insulin, bioavailable testosterone, and IGFBP-1 in the effects of ASAT on obesity-related cancers." (PMID 40987470, 2025). "Moreover, a recent review reported that intermittent fasting may reduce androgen markers (e.g., testosterone and free androgen index) while increasing sex hormone-binding globulin in premenopausal women with obesity—especially when food intake is limited to earlier in the day." (PMID 41010536, 2025). "Hyperinsulinemia further inhibits the synthesis of sex hormone-binding globulin (SHBG), thus forming the “obesity-insulin resistance-reproductive dysfunction” pathophysiological metabolic axis." (PMID 41262938, 2025). "In our study, we compared PCOS patients to hyperinsulinemic/obese adolescents to assess the impact of hyperinsulinemia and obesity on FAI and SHBG." (PMID 40861046, 2025). "In such cases, the presence of a low serum testosterone, with proportionately low serum SHBG and normal-range serum LH and FSH (typical features of the pseudo-hypogonadism of obesity) in conjunction with a normal testicular examination is reassuring." (PMID 40052430, 2025). "Sons of mothers with pre-pregnancy overweight or obesity presented with an altered reproductive hormonal profile characterized by higher levels of oestradiol, LH, and FAI, and lower levels of SHBG." (PMID 37935951, 2024). "Our result is in accordance with the studies: PCOS women have relatively higher LH and SHBG as well as lower WC than controls, despite the similar androgen levels between PCOS and the controls with both obesity and HA." (PMID 38256617, 2024). "At the end of the study, 76% of patients switched from obesity to overweight, 96% of participants had normalization HOMA-IR, serum AMH levels significantly decreased, and progesterone and SHBG significantly increased after VLCKD." (PMID 39328462, 2024). "On these bases, we designed the present study to explore the impact of BS on SHBG, as well as the potential role of SHBG as reliable biomarker for predicting TWL and WR after BS in patients with obesity." (PMID 38183592, 2024). "SHBG was associated inversely with prostate cancer risk in men overall (HRper_SD = 0.918; 95% CI = 0.895 to 0.941), with little evidence for interactions with obesity or diabetes, but with some evidence for an inverse multiplicative interaction with HI (pMI = 0.024)." (PMID 38234143, 2024). "Obesity and impaired fasting glucose (IGF) were more frequently diagnosed in a subgroup with SHBG below 26.1 nmol/L (59.1% vs. 18.6%; p < 0.001 and 17.2% vs. 6.7%; p < 0.001, respectively)." (PMID 36968815, 2023). "SHBG, by downregulating de novo lipogenesis, reduces intrahepatic lipids, which increase in the presence of T2DM, obesity, and PCOS." (PMID 36235799, 2022). "After LSG, patients with obesity and PCOS had decreased free androgens, increased SHBG, and decreased ovarian volume to normal range." (PMID 36686491, 2022). "Obesity, hyperinsulinemia, and increased IGF-I will decrease sex hormone binding globulin (SHBG) leading to increasing of estrogen bioavailability." (PMID 33482868, 2021). "Usually, obesity may be responsible for the Gn resistance during ovarian stimulation according to the previous research, possibly due to the overstimulation of ovarian steroidogenesis and decrease of sex hormone-binding globulin blood concentrations mediated by insulin." (PMID 34584537, 2021). "SHBG and FT4 were reduced, and TSH tended to be elevated in children with obesity constantly throughout childhood and adolescence." (PMID 34386750, 2021). "For example, in a study that carried out dietary control and physical exercises for four months for female of severe obesity suffering from PCOS, the results showed improvement in the level of total testosterone and SHBG." (PMID 33396852, 2020).
Obesity (continued). "Moreover, in this study we show that the SHBG rs1799941 polymorphism differed among types of obesity-related hypogonadism in young non-diabetic males and might provide discriminatory potential to identify subjects with normal FT HG." (PMID 31370189, 2019). "Because of obesity and IR, hyperinsulinemia in women with PCOS would further elevate the bioavailable androgen levels through lowering SHBG level." (PMID 31652273, 2019). "In addition, obesity might also be involved in the relationship between SHBG and atherosclerosis." (PMID 29213285, 2017). "Therefore, obesity might also be involved in the relationship between SHBG and atherosclerosis." (PMID 29213285, 2017). "Men with obesity, the metabolic syndrome, and T2DM have low total and free testosterone and low sex hormone-binding globulin (SHBG)." (PMID 25338765, 2014). "Total testosterone, SHBG, and the T/E2 ratio exhibited negative correlations with all 16 obesity-related metrics (P < 0.05)." (PMID 41310874, 2025). "Obesity can result in nonspecific symptoms in conjunction with reduced serum testosterone and serum SHBG." (PMID 40052430, 2025). "What is more, lower SHBG in women with PCOS and co-occurring IR is more likely to manifest obesity." (PMID 40427034, 2025). "Their results revealed no protective effects from SHBG expression on obesity or dysglycemia in either male or female mice." (PMID 41180177, 2025). "However, some proteins were primarily affected by other factors: SHBG by age and obesity; PRG4 by obesity; and IGF1 and RBP4 by age." (PMID 39972214, 2025). "Obese men exhibit significantly lower serum testosterone and SHBG compared with non-obese men, suggesting that obesity exerts direct effects on androgen status." (PMID 41301438, 2025). "This study shows that aging is followed by an increase in SHBG levels, and areduction in cFT in healthy men without obesity, without significant variation inTT." (PMID 40857627, 2025). "Cross-sectional assessments showed that in males, testosterone levels, SHBG, and T/E2 ratio were negatively correlated with obesity, while estradiol displayed a non-linear, inverted U-shaped relationship." (PMID 41310874, 2025). "Interestingly, lower SHBG levels in women with PCOS and co-occurring IR are found to be a positive factor for obesity." (PMID 40427034, 2025). "Among males, androgens and SHBG showed a significant negative correlation with overall adiposity, while estradiol had a non-linear correlation with obesity." (PMID 41310874, 2025). "(2017) showed that, compared to normal-weight adolescents with PCOS, a group of adolescents with obesity and PCOS had significantly lower levels of SHBG and HDL-C and significantly higher levels of triglycerides, leptin, fasting insulin, LDL-C and free testosterone." (PMID 40491594, 2025). "Additionally, we sought to evaluate the sensitivity of the FAI and SHBG in diagnosing PCOS, particularly in adolescents with complicating factors such as obesity and hyperinsulinemia." (PMID 40861046, 2025). "This also fully explains the negative correlation between obesity, gout, and hyperuricemia accompanied by low-grade chronic inflammation and SHBG levels." (PMID 38751428, 2024). "We found the mediating effect of SHBG, which was independent of confounding factor and some of potential intermediate factors including age and obesity." (PMID 38954350, 2024). "In obesity, as a negative metabolic indicator, there is a reduced level of SHBG, favoring an increase in free estrogen and the carcinogenesis of tissues sensitive to this hormone." (PMID 38768058, 2024). "Plasma SHBG levels, which are low in obesity, increase 1 month after BS but there is no data of plasma SHBG levels at long term." (PMID 38183592, 2024). "Our results are inconsistent with previously observed declines in SHBG in women with obesity, but the relationship between SHBG and testosterone has not been reported in current studies of sex hormones in men with obesity." (PMID 38509558, 2024).
Obesity (continued). "Increased PCSK9 expression induced by dyslipidemia inhibited SHBG synthesis in the liver, which indicated that PCSK9 may be the core of obesity-related abnormal T synthesis." (PMID 37935689, 2023). "However, in men with a high prevalence of obesity or T2DM and those with conditions that affect SHBG levels, low total testosterone levels cannot reliably predict biochemical hypogonadism." (PMID 36876281, 2023). "Obesity usually exacerbates PCOS through the production of adipokines and the reduction of SHBG." (PMID 36967808, 2023). "Our results, driven by genetically determined childhood/adolescent body composition, higher BMI, hyperinsulinaemia, and lower SHBG, clearly favour obesity driving the metabolic, but not reproductive, PCOS phenotype." (PMID 37015099, 2023). "There is a negative correlation between the degree of obesity, as measured by the BMI, and levels of total testosterone and SHBG." (PMID 38203349, 2023). "A total of 230 women (11.8%) had high TT levels (median, 20.2 ng/dL; IQR, 13.6-29.0 ng/dL), 210 (10.4%) had low SHBG levels (median, 567.6 μg/mL; IQR, 379.9-838.9 μg/mL), 825 (39.8%) had obesity (BMI: median, 27.9; IQR, 23.5-33.4), and 965 (45.5%) had metabolic syndrome (weighted percentages)." (PMID 36149653, 2022). "Conversely, serum SHBG levels are reduced in T2DM, obesity, and PCOS." (PMID 36235799, 2022). "The results demonstrated that biologically available testosterone and sex hormone-binding globulin are independently predictive of incident obesity and severe obesity in menopausal women, regardless of age." (PMID 35814604, 2022). "Moreover, the bioavailability of testosterone and estradiol is increased in obesity due to hyperinsulinemia and elevated IGF-1 activity, resulting in decreased hepatic production of SHBG." (PMID 36401194, 2022). "The exact mechanism by which obesity leads to a decrease in serum SHBG levels in humans is not fully understood, although it is likely to be multifactorial." (PMID 33715205, 2021). "Similar results were earlier obtained in Chinese women with PCOS, in whom decreased concentrations of SHBG were closely associated with decreased levels of HDL-C, independent of IR or obesity." (PMID 34501389, 2021). "Our findings support the notion that AE and BE, by increasing endogenous circulating SHBG, are potential non-pharmacological options against obesity and MS-related fatty liver disease." (PMID 33664334, 2021). "In obesity, circulating SHBG levels are decreased to 50% in obese adult women (nonmenopause) compared with lean control patients." (PMID 34335746, 2021). "Moreover, subjects with obesity had significantly higher C-reactive protein (CRP) and TNFα-R1 and reduced SHBG and adiponectin plasma levels compared to the normal-weight controls." (PMID 33689083, 2021). "The relationship between obesity and PCOS is partly related to the negative influence of obesity on SHBG synthesis and secretion, which in turn increases testosterone bioavailability." (PMID 33139661, 2020). "The clinical phenotype is further worsened as a result of excessive ovarian and adrenal androgen release as well as hepatic sex hormone-binding globulin (SHBG) which secretion is independent of obesity." (PMID 32492805, 2020). "Obesity was characterized by increased levels of free T, total and free E2, hsCRP, fasting insulin and glucose, greater WC, WHR and HOMA-IR, and by decreased SHBG and ISI value." (PMID 31652917, 2019). "Based on these findings, it was hypothesized that low TT levels in subjects with obesity and hypogonadism are due to the estradiol-related HPT axis suppression and low levels of SHBG." (PMID 31817436, 2019). "TT has been shown to decrease with obesity together with SHBG levels, producing compensation and no changes in FT." (PMID 31370189, 2019).